ACSL1 (acyl-CoA synthetase long chain family member 1)
Diseases named in the same sentence as ACSL1 in open-access papers (continued):
Sharing a sentence is not in itself a finding about the gene and the disease.
diabetes (18 papers, 2012 to 2025). "ACSL1 has emerged as a mediator of enhanced atherosclerosis associated with diabetes by accelerating the progression of atherosclerosis." (PMID 36054206, 2022). "ACSL1 is induced in classically activated inflammatory macrophages and is causal to the enhanced inflammation and atherosclerosis associated with diabetes in mouse models." (PMID 30300410, 2018). "Diabetic nephropathy, a major complication of diabetes has been linked to ACSL1." (PMID 41288931, 2025). "Furthermore, the ACSL1 deficiency model significantly reduced the release of proinflammatory cytokines and chemokines and prevented diabetic atherosclerosis." (PMID 35869105, 2022). "Tbc1d4, Acadl, Acsl1 and Fabp4 were found to be associated with early diabetes in GK rats for the first time, which may provide a new scope for pathogenesis of postprandial hyperglycemia." (PMID 31141985, 2019). "This is the first study that suggests Tbc1d4, Acadl, Acsl1 and Fabp4 are associated with early diabetes in GK rats, which may provide a new scope for pathogenesis of postprandial hyperglycemia and controlling postprandial glucose levels in T2D patients at early stages." (PMID 31141985, 2019). "Research suggests that ACSL1 plays a critical role in mediating the inflammatory phenotype of macrophages in diabetes and atherosclerosis." (PMID 39908200, 2025). "In summary, the current report provides a molecular framework to understand the mechanisms that explain the pro-atherogenicity of ACSL1 in diabetes." (PMID 36054206, 2022). "We have demonstrated that the ACSL1 is a molecular target of CE for diabetes, both in cell subjects and mouse models of diabetes; CE specifically decreased ACSL1 levels in adipocytes." (PMID 35869105, 2022). "As insulin resistance has been associated with the progressive development of type 2 diabetes mellitus, natural compounds that reduce ACSL1 due to a stimulated AMPK signal should have a significant clinical impact on type 2 diabetes mellitus." (PMID 35869105, 2022). "It has also been reported that individuals with diabetes have higher levels of ACSL1 mRNA in circulating inflammatory monocytes." (PMID 36054206, 2022). "Acsl1 expression is increased by hyperglycemia and inflammatory stimuli in monocytes and macrophages, and promotes the pro-atherosclerotic effects of diabetes in mice." (PMID 36054206, 2022). "Taken together, the reduced levels of cholesterol efflux and expression of ABCA1 in mouse macrophages in the context of diabetes and elevated fatty load were partly mediated by ACSL1." (PMID 28883907, 2017). "Moreover, there was increased expression of Acsl1 when macrophages were cultured under diabetes-relevant high glucose (25 mM) compared to normal glucose (5.5 mM), suggesting that the effect of hyperglycemia on Acsl1 expression is cell-autonomous." (PMID 36054206, 2022). "To determine whether Acsl1 expression is upregulated by diabetes-relevant high glucose, we differentiated primary mouse bone marrow-derived macrophages (BMDMs) under normal glucose (NG; 5.5 mM glucose) or high glucose (HG; 25 mM glucose) conditions." (PMID 36054206, 2022). "In addition, the myeloid cell-specific deletion of ACSL1 in a diabetic mouse model prevented the formation of the inflammatory macrophage phenotype and development of diabetes." (PMID 34299302, 2021). "Myeloid cell-targeted deletion of ACSL1 also prevented diabetes-accelerated atherosclerosis, demonstrating the important role of fatty acid metabolism in atherosclerosis in the setting of diabetes." (PMID 32118048, 2020). "Moreover, ACSL1 polymorphisms confer a higher risk for pre-diabetes mellitus (pre-DM)." (PMID 31929791, 2019). "In addition to ACSL1, ACSL4 has been implicated in diabetes and complications." (PMID 41288931, 2025). "Thus, ACSL1 is a crucial regulator of the pro-atherosclerotic effects of diabetes." (PMID 36054206, 2022).
diabetes (continued). "Our findings indicate that ACSL1 is an important factor in mediating the AMPK signal activation in adipocytes and in regulating glucose tolerance in diabetes." (PMID 35869105, 2022). "SREBP is involved in the regulation of various lipogenic genes such as ACACA, FASN, ACSL1 and MCAT which are found to be overexpressed in diabetes." (PMID 31569751, 2019). "Increases in long-chain acyl-COA synthetase 1 (ACSL1), toll-like receptor (TLR) 2, and TLR4 contribute to the increased inflammatory monocyte/macrophage phenotype in the context of diabetes." (PMID 28883907, 2017). "Significantly, mice lacking Acsl1 in monocytes and macrophages prevented the accelerated progression of atherosclerosis in diabetes." (PMID 36054206, 2022).
ovarian carcinoma (17 papers, 2016 to 2025). A malignant neoplasm originating from the surface ovarian epithelium. "An increased expression of ACSL1 has been found in different cancer types, associated with oncogenic functions in liver, colorectal, prostate, breast, and ovarian cancers." (PMID 38539505, 2024). "We then investigated the association between antioxidant-related proteins with ACSL1 in various ovarian cancer cell lines." (PMID 36882396, 2023). "On one hand, ACSL1 can confer resistance to ferroptosis in ovarian cancer by increasing the N-myristoylation and stability of FSP110." (PMID 40042449, 2025). "ACSL1 promotes the progression of ovarian cancer by regulating FSP1 myristoylation to increase antioxidant capacity and ferroptosis resistance." (PMID 39524444, 2024). "Recent studies have demonstrated significant up-regulation of ACSL1 and ACSL3 protein levels in highly metastatic ovarian cancer cell lines, with gene expression associated with increased metastatic capacity and poor survival prognosis." (PMID 38957470, 2024). "ACSL1 reduces the level of lipid peroxidation and enhances ferroptosis resistance in ovarian cancer through increasing the stability of FSP1." (PMID 37842240, 2023). "ACSL1 is involved in metabolic reprogramming and helps maintain cell survival during the formation of ovarian cancer spheroids." (PMID 36882396, 2023). "ACSL1 overexpression significantly improves proliferation of ovarian cancer cells, induces cancer spheroid formation, and tumorigenesis in xenograft model through enhanced myristic acid (MA) production and therefore increased protein N-myristoylation." (PMID 36882396, 2023). "The results indicated that the high expression of ACSL1 contributed to the metastasis of ovarian cancer and resisted the ferroptosis of cancer cells during the metastasis." (PMID 36882396, 2023). "In this study, three ferroptosis-related genes PRNP, ACSL1, and CP were picked out as the co-DEGs among different ovarian cancer datasets, with significantly decreased expression of PRNP and ACSL1 and increased expression of CP in ovarian cancer tissues when compared with normal ovarian tissues." (PMID 36213323, 2022). "Therefore, we proposed that the increase in ACSL1 and antioxidation during spheroid formation may be involved in the development of drug resistant cells in ovarian cancer cells." (PMID 36882396, 2023). "Our recent study suggested that ACSL1 and ACSL3 protein levels are significantly up-regulated in the highly metastatic ovarian cancer cell lines and their gene expressions are correlated with metastatic capacity and poor survival prognosis." (PMID 36882396, 2023). "ACSL1 and FSP1 expression was significantly higher in metastatic tumors in the omentum than in tumors of the normal ovary and in primary ovarian cancer, while the expression of 4-HNE and PTGS2 was lower in the omentum metastasis tumor." (PMID 36882396, 2023). "Similarly, acyl-CoA synthetase long chain family member 1 (ACSL1) acts as a negative regulator of ferroptosis and increases chemoresistance by up-regulating ferroptosis suppressor 1 (FSP1) in ovarian cancer cells." (PMID 41502518, 2025). "Overexpression of ACSL1-WT rather than ACSL1-MT can reduce carboplatin cytotoxic and increase spheroid formation in ovarian cancer OVCA429 and HM cell lines." (PMID 36882396, 2023). "Previously, we demonstrated that Acyl-CoA synthetase long-chain family member 1 (ACSL1) promotes cell survival and peritoneal metastases in ovarian cancer, but the mechanism is still not well elucidated." (PMID 36882396, 2023). "ACSL1 overexpression in non-metastatic ovarian cancer cells increases their metastatic dissemination in xenograft models, indicating that ACSL1 activity can drive metastasis." (PMID 35634242, 2022).
ovarian carcinoma (continued). "A recent study also showed that long-chain fatty-acid CoA ligase 1 (ACSL1) expression can convert the lipid profile of nonmetastatic ovarian cancer cells to a profile similar to that of highly metastatic ovarian cancer cells and make them highly aggressive." (PMID 35115500, 2022). "In addition, acyl-CoA synthetase long chain family member 1 (ACSL1), a regulator of fatty acid metabolism, inhibits the degradation of FSP1 by increasing its N-myristoylation, thereby antagonizing ferroptosis in ovarian cancer." (PMID 39624080, 2024).
Hepatic steatosis (13 papers, 2016 to 2025). Steatosis is a term used to denote lipid accumulation within hepatocytes. "Proteins associated with liver steatosis are central to β-oxidation, for example, acyl-CoA synthetase long chain family member 1 (ACSL1) breaks down long chain fatty acids." (PMID 39729908, 2025). "Finally, we show that L-carnitine, which buffers excess acetyl-CoA, decreases the ER-associated ACSL1 and alleviates hepatic steatosis." (PMID 37503004, 2023). "Accumulated data have further revealed that ACSL1 activates FFA β-oxidation in the liver to improve hepatic steatosis in vitro and in vivo." (PMID 39834822, 2024). "We provide empirical evidence that L-carnitine inhibits ER translocation of ACSL1 and hepatic steatosis by buffering acetyl-CoA." (PMID 37503004, 2023). "Dysregulated acetyl-CoA induces hepatic steatosis via ACSL1-mediated TG synthesis in the ER19,20,68." (PMID 37503004, 2023). "We found that the hepatic steatosis is driven by increased fatty acid partitioning to the endoplasmic reticulum (ER) for re-esterification via acyl-CoA synthetase long-chain family member 1 (ACSL1)." (PMID 37503004, 2023). "To understand how ACSL1 induces hepatic steatosis in Hmgcs2ΔLiv mice, we assessed the subcellular localization of ACSL1." (PMID 37503004, 2023). "The activation of acyl-CoA-synthetase by ACSL1 promotes the fatty acid accumulation, indicating the potential target for hepatic steatosis." (PMID 27171439, 2016). "We discover that Phb1/2 is an important transcription coregulator in the process of ethanol metabolism, and one identified fatty acid metabolism enzyme Acsl1/5, whose inhibition protects cells and mice from lipid accumulation, a key symptom of hepatic steatosis." (PMID 40858584, 2025). "Ketogenic insufficiency induces hepatic steatosis via ACSL1." (PMID 37503004, 2023). "The results showed that the four genes (ACSL1, ACSL5, EHHADH, and ACAA1) were significantly upregulated in the hepatic tissues of dairy goats with fatty liver." (PMID 40723475, 2025). "Collectively, the results suggest that ACSL1, ACSL5, EHHADH, and ACAA1 play an important role in the development of fatty liver disease in dairy goats." (PMID 40723475, 2025). "The upregulated mitochondrial protein OPA3 is a crucial regulator of mitochondrial function, whereas the expression levels of ACSL1 and MPC1 are directly correlated with hepatic steatosis." (PMID 39280921, 2024). "Indeed, we observed significantly elevated gene expression of ACSL1, ACSL5, EHHADH, and ACAA1 in the hepatic tissues of periparturient goats affected by fatty liver disease." (PMID 40723475, 2025). "Notably, by observing the overlap among these three sub-networks, we found that proteins with downregulated ubiquitination—such as ACSL1, ACSL5, EHHADH, and ACAA1—were transcriptionally upregulated in dairy goats with fatty liver." (PMID 40723475, 2025). "We speculate that the altered ubiquitination of ACSL1, ACSL5, EHHADH, and ACAA1 contributes to their increased hepatic protein levels and abnormal subcellular localization in dairy goats with fatty liver." (PMID 40723475, 2025). "Consistent with this study, it was reported that HIF-2 downregulated the expression of both ACSL1 and carnitine palmitoyltransferase- (CPT-) 1 in rat hepatocytes, which induced the development of hepatic steatosis through the suppression of fatty acid oxidation in mitochondria." (PMID 31089396, 2019).
acute myocardial infarction (12 papers, 2020 to 2025). Necrosis of the myocardium, as a result of interruption of the blood supply to the area. "An intronic variant (rs60780116) in ACSL1 has been associated with risk of Type 2 diabetes and elevated expression of ACSL1 has been shown to be an independent risk factor for acute myocardial infarction after taking into account conventional risk factors." (PMID 32150548, 2020). "ACSL-1 level can be monitored in peripheral blood leukocytes and it was shown that it may be a molecular marker when determining the risk of acute myocardial infarction in humans." (PMID 33716957, 2021). "We showed that the myocardial infarction area was notably reduced by interfering with DNase I and GSK484 treatment, knockdown ACSL1 in vivo also reduced the myocardial infarction area in mIRI mice." (PMID 39853712, 2025). "Inhibition of ACSL1 has been shown to significantly enhance myocardial repair following myocardial infarction in mice." (PMID 40428342, 2025). "A risk nomogram was established by ACSL1, ALDH2, CYP27A1 and PPARA, demonstrating a good ability for DCM and myocardial infarction prediction." (PMID 37056578, 2023). "In clinical cohort studies, high expression of long-chain acyl-coenzyme A synthetases 1 (ACSL1 gene) in peripheral white blood cells of patients with acute myocardial infarction (AMI) has been utilized as molecular markers of myocardial infarction diagnosis." (PMID 32218693, 2020). "ACSL1 is upregulated in both hyperlipidaemia and acute myocardial infarction." (PMID 40176064, 2025). "Interestingly, ACSL1 increases in acute myocardial infarction patients, which is one of the symptoms of chronic Chagas disease." (PMID 39000601, 2024). "This is consistent with recent reports showing increased ACSL1 mRNA in septic patients and patients with acute myocardial infarction compared to controls, which may reflect an inflammatory response from necrotic tissue as a result of ischemia." (PMID 36054206, 2022). "The findings revealed a significant upregulation in the protein and mRAN expression levels of ACSL1, IL1B, and GABARAPL1 in both the hypoxic cell model and myocardial infarction animal model compared to the control group." (PMID 40287718, 2025).
colorectal cancer (12 papers, 2016 to 2025). A primary or metastatic malignant neoplasm that affects the colon or rectum. "One study revealed that upregulation of genes (ABCA1, ACSL1, AGPAT1, and SCD) related to lipogenesis and cholesterol synthesis pathways was associated with poor survival outcomes in colorectal cancer patients." (PMID 34557266, 2021). "ACSL1 and ACSL4 overexpression was associated with a poor clinical outcome in stage II colorectal cancer patients." (PMID 33030783, 2020). "Conversely, the shRNA-mediated knockdown of ACSL1 or ACSL4 reduces cell proliferation in colorectal cancer cell lines, with a more marked effect elicited by the ACSL4 knockdown." (PMID 31344914, 2019). "Three main ACSL isoforms have been found to be upregulated in colorectal cancer, ACSL1, ACSL4 and ACSL6." (PMID 31344914, 2019). "The shRNA-mediated knockdown of ACSL1 in colorectal cancer shows reduced cell proliferation and migration." (PMID 31344914, 2019). "Combination of the gene expression analysis from Oncomine and survival analysis from PrognoScan or Kaplan-Meier plotter revealed the oncogenic role of ACSL1 in colorectal cancer and the tumor suppressor role for ACSL1 in lung cancer." (PMID 27171439, 2016). "And patients with stage II colorectal cancer with higher ACSL1 levels had poorer clinical outcomes." (PMID 37608295, 2023). "However, many prior reports have revealed that ACSL1 was up-regulated in prostate, ovarian and colorectal cancers." (PMID 37608295, 2023). "Various studies have shown that the ACSL1 gene may regulate colorectal cancer through lipid metabolism." (PMID 36482895, 2022). "Moreover, in colorectal cancer cells, ACSL4 overexpression and, to a lesser extent ACSL1, cause a shift of energy metabolism towards glucose utilization." (PMID 31344914, 2019). "This suggests a role of ACSL1 as a direct therapeutic target for colorectal cancer." (PMID 31344914, 2019). "However, overexpression of either ACSL1 or ACSL4 in colorectal cancer cells is sufficient to increase wound healing, cell invasion and proliferation compared to empty vector control cells." (PMID 31344914, 2019). "The breast and colorectal cancer patients with higher ACSL1 expression has poor survival." (PMID 27171439, 2016). "The analysis revealed that ACSL1 may be involved in immune response and cell chemotaxis in colorectal cancer and response to stress in lung cancer." (PMID 27171439, 2016). "The network of ACSL1, ACSL4 and steraroyl-CoA desaturase-1 (SCD), which catalyzes the conversion of SFA into MUFA, is demonstrated to induce EMT program and the higher expression level of ACSL1/ACSL4/SCD is associated with the poorer survival outcome in colorectal cancer." (PMID 27171439, 2016). "Moreover, given the involvement of ACSL1 in favoring glycolysis, a potentially interesting treatment opportunity may arise from the combination of ACSL1 and glycolysis intermediates inhibition in colorectal cancer." (PMID 31344914, 2019). "The genomic coding sequence of ABCA1, ACSL1, AGPAT1 and SCD genes, as well as, their differential expression in a genome-wide expression meta-analysis in colorectal cancer patients were explored." (PMID 29464044, 2018). "Another interesting relationship between colorectal cancer and ACSLs involves the regulation of ACSL1 and ACSL4 by non-canonical micro-RNAs (miRNAs)." (PMID 31344914, 2019). "Similar to ACSL1, ACSL4 is shown to have the potential for colorectal carcinoma treatment." (PMID 31344914, 2019). "As suggested by Cruz-Gill and colleagues, the inhibitory effect of miR-19b-1 on ACSL1, ACSL4 and SCD1 in colorectal carcinoma could be exploited as a therapeutic strategy." (PMID 31344914, 2019).